RNU4-34P (RNA, U4 small nuclear 34, pseudogene)
Gene: Small nuclear RNA gene on chromosome 17 (29,388,560 to 29,388,683, forward strand). Ensembl gene ENSG00000222363.
Homologues: Orthologues: chimpanzee U4 (99% identical), macaque U4 (92% identical), mouse Gm25270 (66% identical), rat U4 (57% identical), dog U4 (56% identical), guinea pig U4 (53% identical). Paralogues in human: RNU4-17P (67% identical), RNU4-49P (63% identical), RNU4-10P (62% identical), RNU4-4P (62% identical), RNU4-46P (61% identical), RNU4-91P (61% identical), RNU4-30P (60% identical), RNU4-51P (60% identical), RNU4-53P (60% identical), RNU4-11P (60% identical), RNU4-15P (60% identical), RNU4-52P (60% identical), and 81 more.